CEACAM6 (CEA cell adhesion molecule 6)
Diseases named in the same sentence as CEACAM6 in open-access papers (continued):
Sharing a sentence is not in itself a finding about the gene and the disease.
non-small cell lung carcinoma (7 papers, 2007 to 2025). A group of at least three distinct histological types of lung cancer, including non-small cell squamous cell carcinoma, adenocarcinoma, and large cell carcinoma. "Exploration of the role of CEACAM6 in non-small cell lung cancer LM using RNA analysis of CSF identified CEACAM6 as highly expressed in tumor-associated cell-free RNA." (PMID 40510352, 2025). "Functional experiments demonstrated that CEACAM6 enhances non-small cell lung cancer cell migration, suggesting its potential as a non-invasive biomarker for LM diagnosis." (PMID 40510352, 2025). "We previously identified CEACAM6 as a novel therapeutic target for non-small-cell lung cancer (NSCLC)." (PMID 40282889, 2025). "Many breast, pancreatic, colonic and non-small-cell lung carcinoma lines express CEACAM6 (NCA-90) and CEACAM5 (carcinoembryonic antigen, CEA), and antibodies to both can affect tumor cell growth in vitro and in vivo." (PMID 17201906, 2007). "In conclusion, CEACAM6 as detected by AP11, may serve as a marker for mucin-producing adenocarcinomas of the gastrointestinal tract and ovary as well as non-small cell lung cancer." (PMID 25427744, 2015).
pancreatic ductal adenocarcinoma (7 papers, 2019 to 2026). An infiltrating adenocarcinoma that arises from the epithelial cells of the pancreas. "CEACAM6 was found to inhibit anoikis in the pancreatic ductal adenocarcinoma (PDA) line MiaPaca2, and inhibition of CEACAM6 with short interfering RNA (siRNA) led to decreased metastasis in a nude mouse orthotopic xenograft model." (PMID 36741860, 2023). "We investigated biomarker CEACAM6, a highly abundant cell surface adhesion receptor that modulates the extracellular matrix (ECM) in pancreatic ductal adenocarcinoma (PDA)." (PMID 31797958, 2019).
breast tumors (6 papers, 2007 to 2025). "previously reported higher CEACAM6 expression in tamoxifen-resistant breast tumors, implicating it in endocrine resistance." (PMID 40936892, 2025). "To analyze the distribution of CEACAM5 expression in different subtypes of breast tumors, we examined a sample of frozen biopsies of which some previously have been utilized for testing CEACAM6-expression." (PMID 33196697, 2020). "The results show a correspondence between CEACAM6 mRNA and protein levels in these tumors, suggesting that, like CEACAM6 mRNA, CEACAM6 protein is similarly elevated in primary breast tumors." (PMID 23592399, 2013). "Together, these results show concordance between PDEF and CEACAM6 expression and elevated co-expression of these molecules in primary breast tumors." (PMID 23592399, 2013). "In contrast, our analysis used the qRT-PCR, Western blotting and immunohistochemistry methods and found highly elevated expression of CEACAM6 in most breast tumors." (PMID 23592399, 2013). "Overall, these results showed elevated co-expression of PDEF and CEACAM6 in 67% of Her2+ breast tumors, but significantly less frequent (24%) elevated co-expression of these molecules in triple-negative tumors." (PMID 23592399, 2013). "Notably, 322 CSR transcripts were significantly elevated in breast tumours compared to healthy breast tissue, with CEACAM6 (log2FC = 8.8), KCNJ (8.4), and CLDN6 (7.6) among the most upregulated." (PMID 38306344, 2024). "Perhaps the most important findings of this study are the elevated co-expression of PDEF and CEACAM6 in a high percentage (72%) of the primary human breast tumors and the essential role of these molecules in the survival of the human breast tumor cell lines." (PMID 23592399, 2013). "Presumably, the availability of specific co-activators/transcription regulators in the luminal versus basal epithelial breast tumor cell lines may differ and lead to the differences in the regulation of CEACAM6 by PDEF." (PMID 23592399, 2013). "The importance of PDEF and CEACAM6 as targets is further evident when considering the results from the comprehensive genome wide sequencing and expression analysis of a large number of human breast tumors [reviewed in 32 and 33]." (PMID 23592399, 2013). "How PDEF and CEACAM6 over expression may promote breast tumor progression may be envisioned as follows." (PMID 23592399, 2013). "The highly frequent over expression of PDEF and CEACAM6 in ER+ breast tumors prompted us to examine whether similar elevated co-expression of these molecules also occurs in Her2 over expressing (Her2+) and triple-negative breast tumors." (PMID 23592399, 2013). "However, further analysis of three of the PDEF induced genes, namely S100A7, CEACAM6 and B7-H4 in primary human breast tumors revealed that only CEACAM6 showed concordance and elevated co-expression with PDEF in primary tumors." (PMID 23592399, 2013). "A total of 110 breast tumors were subjected to immunohistochemical assessment by use of CEACAM5-specific mAbs CB30 and COL-1, CEACAM6 cross-reacting 1105 and CEACAM6-antibody 9A6." (PMID 33196697, 2020). "Overall, 72% (94 of 131) of the primary breast tumors showed 10-fold orhigher expression of both PDEF and CEACAM6." (PMID 23592399, 2013). "Since we previously reported over expression of PDEF in breast tumors and since PDEF induces the expression of S100A7, CEACAM6 and B7-H4 in MCF-7 cells, we tested whether these molecules show concordant and elevated co-expression with PDEF in primary breast tumors." (PMID 23592399, 2013).
cholangiocarcinoma (6 papers, 2006 to 2024). A carcinoma that arises from the intrahepatic biliary tree (intrahepatic cholangiocarcinoma) or from the junction, or adjacent to the junction, of the right and left hepatic ducts (hilar cholangiocarcinoma). "When ROC curves were created to determine the ability of CEACAM6 to predict disease we found that it was slightly more diagnostic of EHCC (AUC = 0.791) than all cholangiocarcinomas combined (AUC = 0.738)." (PMID 26974538, 2016). "ROC curve analysis determined CEACAM6 to be a positive predictor cholangiocarcinoma with a CEACAM6 level >14 ng/ml associated with 87.5% sensitivity, 69.1% specificity, and a likelihood ratio of 2.8 (AUC 0.74)." (PMID 26974538, 2016). "The aim of the present study is to determine if CEACAM6 can be detected in the bile of patients with biliary cancer and can serve as a diagnostic biomarker for cholangiocarcinoma." (PMID 26974538, 2016). "The 90 kDa band corresponding to CEACAM6 was present in both cohorts but was more abundant in the bile of cholangiocarcinoma patients." (PMID 26974538, 2016). "The median concentration of biliary CEACAM6 in patients with benign disease was significantly lower than that of patients with cholangiocarcinoma (7.5 [3.0–22.0] vs. 40.0 [15.0–260.8] ng/ml; p = <.001)." (PMID 26974538, 2016). "Median biliary CEACAM6 levels by ELISA were significantly higher in cholangiocarcinoma patients (40.0 vs. 7.5 ng/ml)." (PMID 26974538, 2016). "We analysed the relation between CEACAM6 expression and gemcitabine sensitivity in cholangiocarcinoma cell lines." (PMID 16868542, 2006). "Our study within cholangiocarcinoma cell lines demonstrated that CEACAM6 overexpressed cells were more chemoresistant to gemcitabine than mock-transfected cells and suppression of CEACAM6 expression by CEACAM6 siRNA increased chemosensitivity to gemcitabine." (PMID 16868542, 2006). "CEACAM6 is a potential prognostic indicator and potential chemoresistant marker to gemcitabine for patients with intrahepatic cholangiocarcinoma." (PMID 16868542, 2006). "Flow cytometry analysis of expression levels of the CEACAM6 protein in cholangiocarcinoma cell lines showed that TFK-1 cells had higher expression levels of the CEACAM6 protein than the other two cell lines (HuCC-T1, MEC)." (PMID 16868542, 2006). "In cholangiocarcinoma, CEACAM6 expression and its relation to clinicopathological factors have not been investigated." (PMID 16868542, 2006). "This study investigates the hypothesis that CEACAM6 concentrations in bile may be a biomarker of malignant disease, with the potential to differentiate cholangiocarcinoma from benign biliary disease." (PMID 26974538, 2016). "The present study demonstrates that biliary CEACAM6 may be potentially more sensitive than current serological, radiographic, or cytological analyses for cholangiocarcinoma." (PMID 26974538, 2016). "The results from this study suggest biliary CEACAM6 may be useful in differentiating cholangiocarcinoma from benign biliary disease." (PMID 26974538, 2016). "By using the area under of the curve (AUC) as a determinant of overall performance of the test, we found that biliary CEACAM6 could differentiate any cholangiocarcinoma (AUC = 0.738) or extrahepatic cholangiocarcinoma (AUC = 0.791) from benign disease." (PMID 26974538, 2016). "Predictive value of CEACAM6 in cholangiocarcinoma by various cut-off criterion." (PMID 26974538, 2016). "In conclusion, this study provided important information that overexpression of CEACAM6 expression may become a prognostic marker and a chemoresistant indicator for gemcitabine in patients with cholangiocarcinoma." (PMID 16868542, 2006). "We examined whether CEACAM6 expression in cholangiocarcinoma cell line (HuCC-T1) would alter sensitivity to gemcitabine." (PMID 16868542, 2006).
cholangiocarcinoma (continued). "Furthermore, we established a CEACAM6 stably transfected human cholangiocarcinoma cell line and examined the biological behaviour of CEACAM6-transfected cells, such as cell growth, invasiveness, resistance to anoikis and gemcitabine chemosensitivity." (PMID 16868542, 2006). "We analysed whether overexpression of CEACAM6 would alter the growth rate of HuCC-T1 cholangiocarcinoma cells." (PMID 16868542, 2006). "Bile CEACAM6 could discriminate cholangiocarcinoma from benign disease (AUC=0.738)." (PMID 36389727, 2022). "Additionally, we investigated effects of CEACAM6 gene in the cholangiocarcinoma cell lines." (PMID 16868542, 2006). "Targeting CEACAM6 may conceivably be a therapeutic approach for patients with cholangiocarcinoma." (PMID 16868542, 2006). "However, in cholangiocarcinoma expression of CEACAM6 and its clinicopathological significance have not been investigated." (PMID 16868542, 2006). "Carcinoembryonic antigen-related cellular adhesion molecule 6 (CEACAM6), which has been reported as a possible biomarker in IPMN and cholangiocarcinoma, was highly up-regulated in PB but not INT IPMN." (PMID 36930707, 2023).
colitis (6 papers, 2013 to 2025). Inflammation of the colon. "Moreover, allelic replacement of the fimH gene in the AIEC LF82 genetic background by fimH from non-pathogenic K12 strains, significantly reduced bacterial colonization and colitis signs in CEABAC10 transgenic mice expressing human CEACAM6." (PMID 28596755, 2017). "In addition, AIEC LF82 induced colitis in CEABAC10 transgenic mice harboring human CEACAM3, CEACAM5, CEACAM6, and CEACAM7 genes, and intraperitoneal injection of anti-CEACAM6 significantly decreased LF82 colonization." (PMID 41163391, 2025).
multiple myeloma (6 papers, 2019 to 2024). "In multiple myeloma, anti-CEACAM6 not only inhibited IFN-γ secretion of ex vivo isolated and resting, but also of polyclonally activated CD8 + T cells from multiple myeloma patients." (PMID 38796667, 2024). "A similar observation has also been reported in multiple myeloma, where binding and cross-linking of CEACAM6 by cytotoxic T-cells inhibited their activation and resulted in T-cell unresponsiveness." (PMID 38279989, 2024). "suggest that CEACAM6 is involved in myeloma disease progression, though the mechanisms are still subject to investigation." (PMID 30809317, 2019). "Blocking CEACAM6 on the surface of myeloma cells restored T-cell reactivity against malignant plasma cells." (PMID 31474761, 2019). "In inflammatory colon disease and multiple myeloma, CEACAM6 is known to activate a subset of immune suppressive CD8+ T-REG cells." (PMID 31797958, 2019). "Multiple myeloma cells expressing CEACAM6 can inhibit myeloma-specific CD8+ T cell reactivity and cytotoxicity." (PMID 30809317, 2019). "Recently, the role of CEACAM6 in the inhibition of CD8+ T-cell responses in multiple myeloma was identified." (PMID 31474761, 2019). "Moreover, CEACAM6 can decrease the host immune response when overexpressed in myeloma cells." (PMID 30809317, 2019). "Moreover, due to high CEACAM6 levels in the bone marrow in RRMM pts., this adhesion molecule might be a therapeutic target in multiple myeloma pts." (PMID 30809317, 2019).
adenoma (5 papers, 2007 to 2023). A neoplasm arising from the epithelium. "CEACAM6 upregulation in the adenoma-normal and cancer-normal comparisons was also noted." (PMID 31211760, 2019). "CEACAM6, another family member of the carcinoembryonic antigen family, is already upregulated in benign precursor lesions like hyperplastic colorectal polyps and early adenomas." (PMID 26673628, 2015). "Similarly, the overexpression of CEACAM6 in hyperplastic polyps and traditional adenomas alike suggests that CEACAM6 may also be involved in these neoplastic pathways." (PMID 17576469, 2007). "And finally, SNORD123, CEACAM6, SNORD78, ANXA10, SPINK1, and CPS1 genes can be used as biomarkers for normal-adenoma comparison." (PMID 37565794, 2023).
melanoma (5 papers, 2013 to 2024). A malignant, usually aggressive tumor composed of atypical, neoplastic melanocytes. "Small-cell carcinomas of the lung, prostatic adenocarcinomas, papillary thyroid carcinomas, malignant melanomas, giant cell tumors, and osteosarcomas were negative for CEACAM6." (PMID 25427744, 2015). "Of the 4 melanomas, 32 osteosarcomas, and 5 giant cell tumors of the bone, none expressed CEACAM6." (PMID 25427744, 2015).
stomach adenocarcinoma (5 papers, 2015 to 2025). "Data from TCGA showed that CEACAM6 mRNA is up regulated in cancer tissues compared to their levels in normal tissues in stomach adenocarcinoma." (PMID 34221964, 2021). "Adenocarcinomas of the stomach (86 %), colorectum (95 %), pancreas (100 %), and lung (83 %), urinary bladder (100 %), and mucinous ovarian tumors (88 %) had a high rate of CEACAM6 immunoreactivity." (PMID 25427744, 2015). "Of the gastric adenocarcinomas, 24 of 28 (86 %) showed CEACAM6 expression." (PMID 25427744, 2015).
acute lymphoblastic leukemia (4 papers, 2005 to 2026). Leukemia with an acute onset, characterized by the presence of lymphoblasts in the bone marrow and the peripheral blood. "In contrast, CEACAM6 up-regulation is associated with an increase in apoptosis in acute lymphoblastic leukaemia (ALL), indicating that the apoptosis-modulating effects of CEACAM6 may be tumour-type-specific." (PMID 23021083, 2012).
hepatocellular carcinoma (4 papers, 2006 to 2024). A malignant tumor that arises from hepatocytes. "Overexpression of CEACAM6 has been observed in various cancers, including lung, breast, colorectal, and hepatocellular cancers, and is associated with poorer overall survival and disease-free survival." (PMID 38796667, 2024). "Interestingly, another study showed that the CEACAM6 gene was one of the most overexpressed genes in a side population of cells of hepatocellular carcinoma." (PMID 16868542, 2006).
invasive breast carcinoma (4 papers, 2015 to 2025). A carcinoma that infiltrates the breast parenchyma. "The expression of CEACAM6 in atypical ductal hyperplasia of the breast (ADH) is strongly associated with the development of invasive breast cancer and might serve as a marker for its early diagnosis." (PMID 25427744, 2015).
ovarian carcinoma (4 papers, 2007 to 2025). A malignant neoplasm originating from the surface ovarian epithelium. "The amount of CEACAM6 in ovarian cancer was highest in mucinous adenocarcinoma (5.6 ± 1.7) > transitional cell (3.8 ± 1.6) > endometrioid (3.6 ± 2.8) > clear cell (3.4 ± 1.8) > yolk sac tumors (2.5 ± 0.5)." (PMID 17201906, 2007). "In ovarian cancers, CEACAM6 expression was highest in mucinous carcinoma (seven out of eight samples, 88 %), whereas only 17 % of serous carcinoma samples were positive for CEACAM6." (PMID 25427744, 2015). "Among the ovarian cancer cells, PEO-1 and OV90 expressed only the lower CEACAM6 molecular weight form." (PMID 32637350, 2020). "TATs highly expressed in cervical cancer include CEACAM5, CD71, CD138, FGFR3, LYPD3, CEACAM6, etc.; VEGF is also highly expressed in ovarian cancer; CD71 and CD138 are highly expressed in endometrial cancer; the TATs highly expressed in uterine sarcoma include B7-H3, DLK1, and EFNA4." (PMID 40046734, 2025).
small cell lung carcinoma (4 papers, 2015 to 2025). Small cell lung cancer (SCLC) is a highly aggressive malignant neoplasm, accounting for 10-15% of lung cancer cases, characterized byrapid growth, and early metastasis. "For small cell lung cancer, ACADSB, CEACAM6, COX6B1, CPXM2 and IL12RB2 continued to show significant associations." (PMID 41340014, 2025). "Our study identified five candidate proteins for small cell lung cancer: ACADSB, CEACAM6, COX6B1, CPXM2 and IL12RB2." (PMID 41340014, 2025). "CEACAM6 was not expressed in small cell lung cancer (SCLC) but in 71 % of non-small cell lung cancer (NSCLC)." (PMID 25427744, 2015).
viral infections (4 papers, 2013 to 2023). "While for CEACAM1, CEACAM5 and CEACAM6 an up-regulation by IFNγ and viral infections has been described in epithelial cells, to our knowledge this is the first report that also type I interferons enhance CEACAM1 expression." (PMID 23941132, 2013). "Since viral infections trigger interferon-induced gene expression in epithelial cells to orchestrate immune responses, we also stained for co-stimulatory molecules CD80 and CD86, or immune-activating molecules CEACAM5 and CEACAM6." (PMID 36827975, 2023).